RB1 (RB transcriptional corepressor 1)
Diseases named in the same sentence as RB1 in open-access papers (continued):
Sharing a sentence is not in itself a finding about the gene and the disease.
tumor (continued). "We first conducted IHC for total Rb1 expression to exclude the loss of Rb1, and we observed that Rb1- negative tumor cells accounted for less than 5% of all tumor cells in tumors from each of the four genotypes, which is consistent with previously published reports." (PMID 28105458, 2016). "Importantly, IHC confirmed the infrequent loss of total Rb1 in these tumors (<5% of tumor cells in a given tumor were negative for Rb1) (data not shown)." (PMID 28105458, 2016). "Given that CDK4/6 inhibitors have been most effective in the context of functional RB1 and low expression or deletion of p16 in other tumor types, these data suggest such agents may merit evaluation in HPV-negative SCCHN, specifically in cases associated with high pT356RB1." (PMID 26265441, 2015). "As RB1 is infrequently mutated in HPV-negative SCCHN, these data suggest that phosphorylation of T356 may serve an important role in functionally inactivating tumor suppression in aggressive disease." (PMID 26265441, 2015). "Indeed, RB1 inhibition confers a proliferative advantage to cells, which could favor tumor development, but the massive apoptosis resulting from RB1 loss could overcome the increased proliferative potential and hinder cancer growth." (PMID 26160835, 2015). "However, similar to other studies, our findings indicated that there is an inverse correlation between the Rb1 and P16 expression according to tumor grade with high expression of the Rb1 in low grade tumors in contrast to high expression of P16 in high grade lesions." (PMID 26043844, 2015). "For RMS, Rb1 had been suggested to play a more important role in embryonal RMS (eRMS) than aRMS: Rb1 genetic abnormalities (allelic imbalance, deletion) are more common in eRMS than in aRMS, and one study showed no dramatic loss of Rb1 in 13 aRMS primary tumor samples." (PMID 24274149, 2013). "The median tumor free survival is 320.5 days for the Rb1∆L/∆L mice compared to 299 days for the Rb1+/+ mice (p=0.0537, log rank test), indicating that Rb1∆L/∆L mice may actually be slightly resistant even though this difference doesn’t reach a 95% confidence interval." (PMID 23936539, 2013). "Moreover, patients with advanced grade tumor (P, 0.50; HR, 1.49; CI, 0.46-4.89) having nodal metastasis (P, 0.42; HR, 1.63; CI, 0.49-5.34) along with RB1 deletion (P, 0.15; HR, 2.27; CI, 0.74-7.02) showed a trend to have poorer survival, albeit being statistically insignificant." (PMID 20226061, 2010).
tumor (continued). "For instance, EGFR amplifications activate PI3K/AKT signaling to fuel tumor growth, while CDK4 gains bypass cell cycle checkpoints, and RB1 losses impair homologous recombination repair." (PMID 40636690, 2025). "At single cell level, RB1 expression is significantly correlated with NUDT15 expression in RB1+NUDT15+ epithelial and other tumor microenvironment cells from PRCA and pan‐cancer patients." (PMID 40904703, 2025). "Losses in tumor suppressor genes such as RB1 and CDKN1B further highlight the genomic instability of this tumor." (PMID 39925800, 2025). "For instance, for CRUK0048, a LUAD tumour with 11 clones, ALPACA inferred LOH affecting 13q12.12–13q14.3 (encompassing BRCA2, PDS5B and RB1) to occur in primary tumour clone 2, before seeding a recurrence metastasis lesion." (PMID 40804524, 2025).
tumor (continued). "Among the targets of Arid4a, MTSS1, RB1, and PTEN are involved in the suppression of tumor cell metastasis, while TIMP2 is believed to be a suppressor of tumor angiogenesis." (PMID 40066676, 2025). "In ASTROs PNC, only one tumour showed a homozygous CDKN2A/B deletion, whilst MYCN amplifications and RB1 alterations were frequently observed." (PMID 39899075, 2025). "Three of these cases also exhibited concurrent alterations in the tumour suppressor genes ARID1A, NF1, or RB1, suggesting even poorer prognosis and a need for more intensive follow‐up or more aggressive interventions beyond EGFR TKI monotherapy." (PMID 41015991, 2025). "Usually, when analyzing the tumor genome by CMA, aberrations larger than 5 MB and additional microdeletions involving the CDKN2A/B, BTG1, EBF1, ETV6, ERG, IKZF1, PAX5, and RB1 genes are taken into account." (PMID 39408811, 2024). "RB1 overlapping with the imprinted region RB1:Int2-DMR, where 46% of NB tumours displayed GOM in our study, has also previously been reported as an independent prognostic biomarker for NB where low RB1 expression correlated with poor prognosis." (PMID 39217334, 2024). "Our study uncovered the crucial tumor-suppressive role of METTL1-mediated tRNA m7G modification in BC by promoting the translation of GADD45A and RB1 mRNAs, selectively blocking the G2/M phase of the cell cycle." (PMID 38822363, 2024). "The analyses showed that the vast majority of tumor samples had methylation of both CDKN2A/p16INK4A (13/15) and RB1 (11/15)." (PMID 38716944, 2024). "We present the case of a patient initially diagnosed with MM with a rare complex karyotype, abnormalities in the IGH, RB1, and D13S319 (13q-) genes, and a high tumor burden." (PMID 38941416, 2024). "Strikingly, the higher gene expression of tumor suppressors RB1 and CDKN2A/p16 was observed in tumor patients compared to normal patients." (PMID 39123441, 2024). "The multivariate analysis included tumour stage and CDK4, CDK6, CDK2, cyclin D1, cyclin E1, RB1 and pRB1 protein expression." (PMID 38612869, 2024). "We examined RB1 expression and germline BRCA status in a subset of 1,134 HGSC, and related genotype to overall survival (OS), tumor-infiltrating CD8+ lymphocytes, and transcriptomic subtypes." (PMID 38837893, 2024). "Regarding the non-tumor tissue, the majority of samples (although slightly less than in tumors) also showed methylation of CDKN2A/p16INK4A (12/15) and RB1 (8/15)." (PMID 38716944, 2024). "We observed that the levels of several genera were differentially affected in phases of end point tumour growth for TRAMP-C2 and both Pten−/−; Rb1+/+ and Pten−/−; Rb1−/− mouse models." (PMID 38654015, 2024).
tumor (continued). "As a master tumor suppressor, P16 inhibits CDK4/6-catalyzed RB1 phosphorylation while simultaneously driving the feedforward degradation of RB1." (PMID 39351198, 2024). "miR-93-5p is often overexpressed in NSCLC and acts as an oncogene by inhibiting the tumor suppressor activities of PTEN and RB1." (PMID 39712244, 2024). "Our work demonstrated that SMAD4 can promote the aggressive tumor behavior and induce NE phenotype and EGFR-TKI and pemetrexed resistance independently of RB1 status for the first time." (PMID 38233864, 2024). "On the other hand, the onco‐suppressor pRb (RB1), the main target of CDK4, has been found to be intact in most MPMs, pointing out these tumours as paradigmatic targets for CDK4/6 inhibitors (CDK4/6i)." (PMID 36453028, 2024). "In TCGA, one grade 4 tumor had both CDKN2A and RB1 called as homozygously deleted but only RB1 showed decreased expression." (PMID 37932833, 2023). "We also examined the expression levels of RB1 and CDKN2B in tumor specimens from five patients with PR and PD using immunohistochemical staining." (PMID 37781033, 2023). "Our data are consistent with those of previous reports that the tumor suppressor properties of the RB1 gene are significantly stronger than those of RBL1 and RBL2 and that among RB family members only RB1 inactivation is commonly found in human cancer." (PMID 36928314, 2023). "We examined RB1 expression and germline BRCA status in a subset of 1134 HGSC, and related genotype to survival, tumour infiltrating CD8+ lymphocyte counts and transcriptomic subtypes." (PMID 37986741, 2023). "We identified amplifications in oncogenes, including FCGR2B and CCND1, and deletions of tumor suppressors, such as CCNC and RB1, only in HPV-negative tumors." (PMID 37461056, 2023).
tumor (continued). "Consistent with the INPP4B tumor suppressor function, the tumorigenic markers MAPK, SRC, and SNAI2 were elevated, and the tumor suppressor proteins RB1, BRCA1, and CHEK2 were decreased in the cells treated with siRNA targeting INPP4B." (PMID 38001678, 2023). "miR-3619-5p inhibited tumor growth in vivo by inducing the phosphorylation of activator of transcription 3 (STAT3) and retinoblastoma protein (Rb1), thereby targeting PSMD10 to inhibit cell proliferation and induce G1 arrest." (PMID 37349676, 2023). "A relatively high level of acquired alterations in RB1 (33%), the histone-lysine methyltransferase KMT2C (29%), and PTEN (19%) were also identified in the PD tumor samples, suggesting a role in driving resistance to therapy in this patient cohort." (PMID 37475004, 2023). "Compared to HES1 (−) tumors, expression levels of Ki67 (p = 0.0268), RB1 (p = 0.0271) and Cyclin D1 (p = 0.0487) were all significantly upregulated in the HES1 (+) tumor cells." (PMID 37749297, 2023). "In exploratory biomarker analyses, focal METamp, RB1 wild-type, MYC diploidy, low circulating tumor DNA (ctDNA) burden at baseline, and early molecular response are associated with better outcomes." (PMID 37944528, 2023). "Especially for LUSC, a comprehensive study of 178 LUSC specimens revealed that significant alteration in CDKN2A and RB1 gene was identified in 72% of LUSC cases, and CDK4/6 gene was frequently amplified in CDKN2A intact tumor." (PMID 36005200, 2022). "In normal eukaryotic cells, the tumour suppressive function of RB1 is executed by its translational product, the RB protein (pRb)." (PMID 35650644, 2022). "In meningioma, MEG3 accelerates tumor suppressor RB1 directly or indirectly by activating CDKN4A, resulting in tumor cell growth arrest." (PMID 35954272, 2022). "Mouse models of SCAs and in vitro studies showed a reduced expression of tumor suppressor genes RB1 and KLK10, and altered expression of other genes related to tumor progression and metastasis." (PMID 35743266, 2022).